IL22 (interleukin 22)
Diseases named in the same sentence as IL22 in open-access papers (continued):
Sharing a sentence is not in itself a finding about the gene and the disease.
psoriasis (continued). "Several types of inflammatory skin diseases (such as psoriasis) are closely related to the activation of JAK/STAT signaling pathway, as the activation of this pathway can enhance the secretion of various pro-inflammatory cytokines (e.g., IL-17, IL-22, IL-23, and TNF-α)." (PMID 36618400, 2022). "Indeed, psoriasis is reported to involve an upregulation of various immune cells (plasmacytoid dendritic and T helper cells), as well as the release of key cytokines such as TNF-a, interleukin-23 (IL-23), IL-17 and IL-22." (PMID 34680331, 2021). "In this study, we found that glycyrrhizin can attenuate the promotion of a-STAT3 induced by SIRT1, which suggests that glycyrrhizin may attenuate the response of keratinocytes to IL-22 by inhibiting the expression of a-STAT3, thereby playing a role in improving psoriasis." (PMID 34044769, 2021). "Further, IL-22 promotes the expression of proinflammatory cytokines including IL-1, TNF-α, and GM-CSF, all of which have been shown to be highly expressed in lesional skin following irritant exposure and are well known to be involved in the pathology of psoriasis." (PMID 31781680, 2019). "The result is compatible with previous reports, as AhR-deficiency in mice resulted in reduced IL-22-secreting CD4+ T cells and more specifically, a psoriasis model demonstrated the requirement of AhR for IL-22 production by Th17, but not by ILC3 and γδ+ T cells." (PMID 30944419, 2019). "Also IFN-γ-induced, but not IL-22-induced IL-6 and IL-20, two psoriasis-related cytokines were inhibited by this drug." (PMID 30581877, 2018). "Increasing evidence suggests that JAK proteins are a potential target for immunosuppressive drugs against psoriasis and other immune-mediated skin diseases, especially those elicited by epidermal keratinocytes exposed to massive amounts of proinflammatory cytokines, including IFN-γ and IL-22." (PMID 30581877, 2018). "Importantly, IL-17- and IL-22-producing cells were strongly reduced by JAK blockade in IMQ-treated skin, similarly to what observed in human psoriasis, where improvement of clinical and histologic signs by tofacitinib was associated with an inhibition of IL-17 gene expression and IL-23/Th17 pathway." (PMID 30581877, 2018). "We also found that IL-22 increases CD147 transcription in vitro and in vivo and that Stat3 binds directly to the CD147 promoter between positions −854 and −440, suggesting that CD147 expression is up-regulated in patients with psoriasis through Stat3 activation." (PMID 28272440, 2017). "In light of our findings, we can hypothesize that the employment of DCE and CS in psoriasis could efficiently counteract the pro-inflammatory effects of IFN-γ and IL-22 on keratinocytes, revert the apoptosis-resistant phenotype, as well as inhibit hyperproliferation in the psoriatic epidermis." (PMID 25226283, 2014). "Interestingly, stimulation of keratinocytes with a combination of IL-17A, IL-22 and TNFα increased S100A7 production, which may form a feed-back loop, amplifying inflammation in psoriasis and other conditions." (PMID 23285311, 2012). "Therefore, our finding that IL-22 induced K17 expression in HaCaT cells by activating STAT3 and ERK1/2 signaling pathways is consistent with the role that these two pathways play in the pathogenesis of psoriasis." (PMID 22808266, 2012). "This CD4 T cell subset may be similar to that recently reported to secrete IL-22 but not IL-17 and to be involved in the skin pathophysiology of psoriasis." (PMID 20929536, 2010). "Interestingly, microarray reports analysing PBMC or psoriatic skin from psoriasis patients have not described differential expression of IL-23, IL-17, or IL-22, although these appear to play an important role in psoriasis pathogenesis." (PMID 19884985, 2009).
psoriasis (continued). "Moreover, IL-22 levels were positively correlated with disease severity as measured by the PASI, supporting the notion that IL-22 expression is not merely a bystander phenomenon but may play an active role in the pathogenesis of psoriasis." (PMID 40731810, 2025). "Moreover, other relevant cytokines such as IL-23, IFN-γand IL-22 were not measured, which may have provided a more comprehensive understanding of the inflammatory network in psoriasis." (PMID 41393395, 2025). "Furthermore, several cytokines such as IFN-γ, interleukin-12 (IL-12), interleukin-22 (IL-22) and IL-23, which are regulated by the Janus Kinase- Signal transducers and activators of transcription (JAK-STAT) signaling pathway, have been identified as having a role in the development of psoriasis." (PMID 39534602, 2024). "While Th17 cells and associated molecules, such as IL-17A, IL-17F, IL-22, and tumor necrosis factor (TNF-a), are known to be elevated in serum and psoriatic skin lesions, recent research suggests that Th17 cells are not the primary source of these pathogenic cytokines in psoriasis." (PMID 38791423, 2024). "Moreover, the strategy of blocking IL-22 has proven to be not effective in treating psoriasis." (PMID 34829740, 2021). "However, the role of IL-22 in the apoptosis of psoriasis has not been reported." (PMID 32632545, 2020). "Finally, to explore the gene expression profile of IL17A, IL22, and IL23A in relation to other genes expressed in psoriatic plaques, we utilized a machine learning nonlinear dimensionality reduction strategy to visualize the entire psoriasis transcriptome as a 2-dimensional (2D) image." (PMID 31019502, 2019). "Additionally, murine models of psoriasis indicate that ILC3s may be a rich source of non-T cell-derived IL-22." (PMID 30109481, 2018). "About two-thirds of our patients also had psoriasis, though mostly minimal disease, and therefore we cannot distinguish the immune consequences of inflammatory joint from inflammatory skin disease, nor determine to which inflammatory site the IL-22+ cells would be directed toward." (PMID 29163483, 2017). "Moreover, using an autoimmune psoriasis model, mice treated with IL-22 neutralizing antibody demonstrated either no development or extremely mild development of psoriasis, which suggests that IL-22 antagonism may lead to a therapeutic approach." (PMID 27595115, 2016). "In the absence of IL-22, the severity of both IL-23-mediated and IMQ-induced psoriasis-like dermatitis in relevant mice models is significantly reduced." (PMID 40906403, 2025). "Interestingly, IL‐22 production was not significantly increased by T cells from healthy volunteers (left), whereas circulating polyclonal T cells from patients with psoriasis showed a significant increase in production of IL‐22 in a CD1a‐dependent manner in response to rAOAH (right)." (PMID 34913478, 2022). "Surprisingly, clinical trials of anti-IL-22 monoclonal antibodies (mAb), ILV-094 (NCT00563524) and ILV-095 (NCT01010542), are discontinued because of no efficacy in psoriasis patients with PASI ≥ 11 and PGA ≥ 3 in active phases." (PMID 35911703, 2022). "Surprisingly, in a psoriasis-like mouse model, it was reported that TH17 cells were not the dominant source of IL-17 and IL-22, rather the RORγt+ gamma delta T (RORγt+ γδ T) cells and ILC3s were." (PMID 34831296, 2021). "This indicates that IL-19 and IL-24, rather than IL-22, IL-17A or IL-17F, were responsible for the late stage (day 10) keratinocyte hyper-proliferation and acanthosis in the IMQ-induced psoriasis mouse model during anti-IL-10 treatment." (PMID 34616394, 2021). "Although the etiology of psoriasis has not yet been fully elucidated, the abnormal production of several inflammatory mediators from immune cells such as TNF-α, IL-6, IL-17, IL-22 and IL-23 are confirmed to play a key role in psoriasis." (PMID 29272319, 2017).
psoriasis (continued). "We found that the addition of Th17 cytokines, IL-17 and IL-22, to the N/TERT-HEEs most closely resembled psoriasis skin: presence of parakeratosis, lack of a stratum granulosum (and thus low levels of FLG and LOR), and induced levels of hBD2 and SKALP." (PMID 28928444, 2017). "Most well known psoriasis related genes activated in non-lesional skin are IL6, IL22, IL36A, IL36G, IL19, IL20, S100A7 and S100A12." (PMID 25897967, 2015). "Furthermore, the percent reduction of the PASI correlated with serum levels of IL-6, but not IL-17 or IL-22, before photo(chemo)therapy, indicating that psoriasis patients with high serum IL-6 levels might be more susceptible to the effects of photo(chemo)therapy." (PMID 23365685, 2013). "However, a significant number of genes which may be induced by IL-23 or IL-22 such as GRO-1 (CXCL1), S100A7, S100A8, STAT3, IL-6, SCYA20 (CCL20), SCYA22 (macrophage-derived chemokine/CCL22), and β-defensin 2 have been identified in psoriasis microarray studies." (PMID 19884985, 2009). "Furthermore, analysis of circulating immune cells in psoriasis confirmed that most of the TH17 cells do not co-express IL-17 and IL-22." (PMID 38642273, 2024). "Therefore, we introduced a novel combination of cytokines, including IL-17A, IL-22, IFN-γ, TNF-α, and KGF as a CytoMix, that had not been previously applied for inducing psoriasis-like inflammation." (PMID 38132145, 2023). "In FFA4 KO mice, the levels of inflammatory TH23/TH17 axis cytokines (IL-17A, IL-22 and IL-23) and TH1 cytokines (IL-1β, IFN-γ and TNF-α) in the lymph nodes were also increased after psoriasis induction; however, Compound A treatment did not suppress the cytokine levels." (PMID 35562873, 2022). "Because IL22 failed to strongly correlate with IL17A and IL23A, the relationships between IL22 and keratin genes were explored across the four independently acquired RNA-Seq psoriasis datasets." (PMID 31019502, 2019). "We also characterised their effects in ex-vivo psoriasis PBMC and report that curcumin, but not carnosol, strongly reduces T cell proliferation and cytokine poly-functionality, with reduced expression of psoriatic cytokines IFNγ, IL-17, GM-CSF and IL-22." (PMID 29980703, 2018). "Likewise, Th17-driven psoriasis was diagnosed in only two of our patients, each of whom lacked autoantibodies to IL17A, IL17F, and IL22 (our unpublished data)." (PMID 27426947, 2016).
colitis (449 papers, 2010 to 2026). Inflammation of the colon. "In contrast, hFcγR mice given IgG from patients with colitis developed colon inflammation marked by a significant increase in submucosal lymphocyte infiltration, goblet cell loss, and circulating cytokines, including IL-1β, IL-17a, and IL-22." (PMID 42282671, 2026). "In contrast, hFcgR mice given IgG from patients with colitis developed colon inflammation marked by a significant increase in submucosal lymphocyte infiltration, goblet cell loss, and circulating cytokines, including IL-6, IL-17, and IL-22." (PMID 42282671, 2026). "Studies have shown that excess IL-22 causes neutrophils to overreact and exacerbate barrier damage, leading to colitis." (PMID 39926427, 2025). "AHR-null mice exhibit enhanced susceptibility to colitis and Citrobacter rodentium infection due to a reduction of ILC3s-derived IL-22 production in the intestine." (PMID 41194916, 2025). "During the reparative phase of intestinal inflammation, ILC3s serve as a paramount source of IL-22; its deficiency can lead to microbial dysbiosis, barrier disruption, and increased susceptibility to colitis in mice." (PMID 41356793, 2025). "Here we report that CR infection causes severe colitis and mortality in interleukin 22 knockout (Il22-/-) and Rag1 knockout (Rag1-/-) mice under germ-free (GF) conditions." (PMID 39630719, 2024). "In the pathogenesis of colitis, IL-6 and IL-22 are inflammation-associated markers that correlate with the activation of the JAK and STAT3 pathways." (PMID 39133435, 2024). "Recently, we demonstrated that the transfer of Card9–/– mice microbiota to GF WT recipient mice was sufficient to recapitulate the defective IL-22 activation and increased colitis susceptibility observed in Card9–/– mice." (PMID 38649950, 2024). "In innate (lymphocyte independent) colitis model, IL-23R-related pathology was associated with IL-22 signaling, as neutralization of IL-22 exhibited protectivity." (PMID 39354587, 2024). "PD-1 expression on ILC3s was induced by colitis caused by dextran sulfate sodium and suppressed IL-22 production in these cells." (PMID 38788198, 2024). "In colitic mice, the administration of I3C triggers an IL-22-dependent mechanism that attenuates colonic inflammation, and prevents the microbial dysbiosis caused by colitis by increasing a subset of Gram-positive bacteria known to produce butyrate." (PMID 38674118, 2024). "Adoptive transfer of T cells deficient in Th17-associated cytokines (IL-17A, IL-17F, and IL-22) into Rag1 knockout mice induced severe colitis comparable to that induced by wild-type cells." (PMID 37239894, 2023). "AHR-deficient mice show increased susceptibility to colitis and Citrobacter rodentium infection due to impaired ILC3s and low IL-22 in the intestine and the decreased number of intraepithelial lymphocytes." (PMID 37304260, 2023). "It has been demonstrated that excessive ILC3 activation appears to aggravate experimental colitis by causing the release of IL-17A and IL-22 and an increase in neutrophil infiltration and tissue destruction in animal colitis models." (PMID 36825081, 2023). "β2-integrins (ITGB2) are required for IL-1β dependent induction of IL-22 by ILC3s, ITGB2 deficiency is associated with impaired IL-22 responses in colitis." (PMID 37016023, 2023). "The microbiota from CARD9 knockout mice showed inhibited Trp metabolism, along with less production of AHR ligands IL-22, which eventually increased the risk of colitis." (PMID 37942478, 2023). "The loss of IL-22 resulted in severe colitis, which was rescued by increasing the expression of IL-22." (PMID 37432218, 2023). "This occurs as Tregs will inhibit ILC3-associated colitis by preventing the secretion of IL-23 and IL-1β from tissue-resident macrophages that block the production of IL-22." (PMID 37901813, 2023).
colitis (continued). "Preclinical data have suggested that IL‐22 or IL‐22 receptor deficiency leads to exacerbated dextran sulphate sodium (DSS)‐induced colitis or T cell‐induced colitis." (PMID 36404603, 2023). "And IL-22 deficiency significantly attenuated colitis in vivo and in vitro, which appears to be associated with reduced levels of ER stress in colonic epithelial tissue." (PMID 37122757, 2023). "Our results verified that DSS caused the upregulation of miR-568 in colitis mice, while treatment with IL-22 attenuated the increase in miR-568 expression." (PMID 36092152, 2022). "Indole-3-acetic acid (I3A) and indole-3-methanol (I3C) produced by Bacteroides ovatus can promote immune cells to produce IL-22 and prevent microbial imbalance caused by colitis, thus have a beneficial impact on colitis." (PMID 36189293, 2022). "This suggests that the impaired production of colonic IL-22 and mucin, which increases the severity of colitis, is caused by vitamin C insufficiency." (PMID 36142515, 2022). "In mice with dextran sulfate sodium (DSS)-induced colitis, Reg3γ protein expression was upregulated and the STAT3-associated cytokines (such as IL-6, IL-17, and IL-22)/Reg3γ axis played a pivotal role in the acute phase of colitis." (PMID 34811636, 2022). "In line with this, we found a reduced secretion of IL-22 in the colon of Rptor-deficient mice during colitis." (PMID 34341503, 2021). "Of note, similar observations have been made for IL-22-producing CD4+ T cells in colitis-associated colon cancer." (PMID 34566952, 2021). "A recent study shows that TGF-β signaling and strong TCR stimulation, coupled with AHR ligands, promote IL-22 production by Th17 cells and cause colitis-associated colon cancer." (PMID 33451114, 2021). "Il23r-deficient mice lacks Il22 expression, and IL-23R-mediated IL-22 production is considerably important for improving colitis." (PMID 34759916, 2021). "We found that Yeti mice display increased levels of ILC3s and that iNKT cell deficiency in Yeti/CD1d KO mice decreases levels of IL22-producing ILC3s during DSS-induced colitis." (PMID 33513946, 2021). "Their adoptive transfer to iNKT cell-deficient animals induced a significant increase in IL22 production by ILC3s, indicating that crosstalk between iNKT cells and ILC3s plays a critical role in modulating colitis in Yeti mice." (PMID 33513946, 2021). "Our own work also supports the notion that heightened IL-22 expression by ILC3s when MSC was deficient has an aggravating effect in DSS-induced murine colitis." (PMID 34992594, 2021). "When the microbiome from IL-22 deficient mice was transmitted to wild-type animals along this led to an increased susceptibility to colitis, suggesting an important role for IL-22 the balance between immunity and colonic microbiota." (PMID 34093536, 2021). "Discoveries in MSC-/- mice support the emerging theory that IL-22 overproduction in colitis underlies intestinal epithelial cell stress response, and call for cautious re-evaluation on IL-22 supplementation therapy for human IBD." (PMID 34992594, 2021). "Card9−/− mice appear to be more susceptible to colitis, have dysbiosis, and a reduction in colonic IL-22 expression." (PMID 34362137, 2021). "As cytokines of the IL-6 and IL-10 families, including IL-6, IL-10, and IL-22, are implicated in supporting intestinal wound healing and immune regulation during colitis, we evaluated the production of these cytokines upon DSS treatment." (PMID 33673239, 2021). "Here we show that changes in the microbial population induced by administration of antibiotics include a bloom of Escherichia coli, which was associated with worsening chemically-induced colitis in IL-22-deficient mice." (PMID 33027280, 2020). "Only in some ILC3 cells involved colitis models, such as anti-CD40 and CD45RBllow transferred colitis models, IL-22 plays a pathogenic role." (PMID 32670290, 2020).